IL13 (interleukin 13)
Diseases named in the same sentence as IL13 in open-access papers (continued):
Sharing a sentence is not in itself a finding about the gene and the disease.
asthma (continued). "Interleukin-13 (IL13) has recently emerged as a primary target for asthma therapy, with ongoing clinical trials targeting IL13 or approved therapeutics targeting its receptor interleukin-4 receptor α (IL4Rα)." (PMID 34305924, 2021). "Whereas IL4 acts predominantly in the early phase of asthma development, IL13 is thought to be active in the late phase of allergic reactions." (PMID 34305924, 2021). "This study revealed the active ingredients and potential molecular mechanism by which MGMD treatment is effective against airway inflammation and remodeling in asthma through regulating IL-4 and IL-13 signaling and SPMs biosynthesis." (PMID 33968984, 2021). "Propolis also showed a wonderful effect on asthma by suppressing eotaxin and IL-13; therefore it has strong potential for, inhibiting eosinophil chemotaxis." (PMID 33628717, 2021). "Th2 and ILC2-derived IL-4, IL-5, and IL-13 generate the typical pathophysiological effects of asthma, including activation and recruitment of eosinophils in the airways, IgE production by activated plasma cells, AHR and airway remodelling." (PMID 34020658, 2021). "Three monoclonal antibodies directed against IL13 (tralokinumab, lebrikizumab and anrukinzumab) were used to interrogate the role of this cytokine in the pathophysiology of severe asthma and responses to treatment." (PMID 34305924, 2021). "In asthma, type III Interferons have been reported to decrease IL-4 and IL-5 production, as well as IL-13 production by T cells providing evidence for a protective role in asthma exacerbations." (PMID 34899691, 2021). "Th2 type of response is one of the main concepts in asthma pathogenesis; here, we consider all γδ T cells producing any of Th2 cytokines (IL-4, IL-5 or IL-13) as Th2-like γδ T." (PMID 33661375, 2021). "In contrast to some models that measured IL-4, in our model we measured the Th2 response through IL-5 and IL-13, because they were able to envelop the parameters of asthma." (PMID 34829186, 2021). "Some of the cytokines produced in excess by patients with severe asthma (including IL-2, IL-4, and IL-13) enhance p38MAPK activity." (PMID 33628371, 2021). "Serum IL-4, IL-9, and IL-13 levels were significantly (p < 0.01) enhanced in the asthma group compared with the control group." (PMID 33577738, 2021). "Ozone exposure leads to an increase in total γδ and IL-13+ γδ cells within lungs of obese mice, the latter seems of particular importance in the pathogenesis of ozone-related asthma exacerbation in obese subjects." (PMID 33661375, 2021). "On the other hand, it is known that recruitment of Th2 cells that secrete IL-4, IL-5 and IL-13 accompanied by eosinophil recruitment to the airways has been considered integral to the pathogenesis of asthma." (PMID 33407843, 2021). "Several studies have suggested that pro-inflammatory cytokines, such as IL-13 and IL-4, which are involved in the pathogenesis of asthma, contribute to the degradation of ZO-1 and occluding." (PMID 33868003, 2021). "We have sought to further understand IL‐13 in the peripheral airways in severe asthma through bronchoalveolar analysis." (PMID 33411348, 2021). "In line with our data in mice, IL-13 also plays an important role in controlling airway reactivity in human asthma." (PMID 33976140, 2021). "Lebrikizumab and tralokinumab, IL-4/IL-13 inhibitors, show clinical efficiency in asthma and AD indication for the shared inflammatory mechanisms in the atopic diseases pathogenesis." (PMID 34911576, 2021). "Interleukin (IL)‐13, a pro‐inflammatory cytokine, has been known as a critical mediator in allergy and asthma." (PMID 33943014, 2021). "The Th2 pathway in asthma can be recognized by increased secretion of IL-4, IL-5, and/or IL-13 resulting in eosinophilic inflammation." (PMID 35387016, 2021).
asthma (continued). "The pro-allergic mechanism of PD-L2 action in asthma mouse model has been suggested to be mediated by diminishing IL-12 production in DC which counterbalancing IL-13 expression as a key type 2 cytokine involved in AHR." (PMID 34185781, 2021). "Some miRNAs have been suggested to affect IL-13 and Th2 response, which are known to be fine-tuners in the mechanism of asthma." (PMID 34899920, 2021). "Chronic airway inflammation in asthma is typically characterized by eosinophil infiltration, overproduction of IgE, and Th2 cytokines, including IL-4, IL-5, and IL-13." (PMID 35008504, 2021). "An alternative source of IL‐4 and IL‐13 are mast cells, a cell population increased within the peripheral airways of severe asthma and whose activation is poorly supressed by steroid therapy." (PMID 33411348, 2021). "Lebrikizumab is a humanized IgG antibody that binds to IL-13, neutralizing its activity and improving lung function in asthma patients." (PMID 34305927, 2021). "ILC2 is of a pivotal role in promoting type 2 responses in asthma through the production of IL-13 and IL-5, with the former involved in bronchial hyperreactivity and the latter in airway eosinophilia." (PMID 33781317, 2021). "These asthma therapies have been directed against interleukin 4/interleukin 13, thymic stromal lymphopoietin, CRTH2 antagonists, and the IL-3/5/GM-CSF axis, and bring the possibility of improved asthma control for patients with severe asthma." (PMID 33917396, 2021). "Given the association of IL-4, IL-5, IL-9, IL-13 and TSLP to asthma pathologies, all have been targeted with antibody-based therapeutics that bind either directly to the cytokines or their receptors." (PMID 34680614, 2021). "BAL IL‐4 and BAL IL‐5 were both increased in the high BAL IL‐13 group compared with the low IL‐13 severe asthma group." (PMID 33411348, 2021). "In a murine model of asthma, neutralization of the Th2 cytokines IL-4 and IL-13 increased Th17 cell number and neutrophilic inflammation in the lung." (PMID 35387016, 2021). "We also captured some significant overlaps of asthma disease features in the terms of pathways, of which the overlapping regulation of inflammation and airway remodeling in Interleukin-4 and Interleukin-13 signaling was especially elaborated." (PMID 34970542, 2021). "The critical role of IL-13 in the IgE production and the eosinophilic pathway, along with the association between IL-13 and asthma severity, led to a shift in focus of the pharmaceutical society to the development of anti-IL-13 agents to treat asthma." (PMID 33673725, 2021). "The essential roles of IL-4 and IL-13 in the pathogenesis of allergic diseases, such as AD and asthma, were proven clinically by the efficacy of dupilumab, a monoclonal antibody for IL-4Rα." (PMID 34691223, 2021). "Our analysis identified the involvement of a novel gene, namely JMJD2B/KDM4B, in the pathogenesis of subepithelial fibrosis in asthma that is responsive to IL-13 stimulation." (PMID 33688506, 2021). "Many people with asthma display evidence of a type 2–high (T2-high) phenotype with atopy and ongoing T2 airway inflammation mediated by the cytokines IL-4, IL-5, and IL-13." (PMID 33682796, 2021). "Here the authors show, in humanized mouse models, that dual vaccination against IL-4 and IL-13 induces their durable suppression ameliorate experimental asthma, and to hint clinical translation." (PMID 33976140, 2021). "Interleukin 13 (IL-13), which drives asthma symptoms or IL-4 and IL-13 enhanced by IFN-gamma, induces changes in the TJ protein composition so that paracellular permeability becomes increased." (PMID 34395412, 2021). "Antibodies for neutralizing IL-4, IL-5, IL-13, and IgE were considered as personalized medicine to improve asthma patient status." (PMID 34595240, 2021). "Endothelial miR-1 levels down-regulated by IL-13 can modulate eosinophil transport in allergic airway inflammation, showing a therapeutic potential in asthma and chronic rhinosinusitis." (PMID 34946955, 2021).
asthma (continued). "In mice that lack IL-4, IL-5, IL-13 reduction of asthma symptoms was observed in the Ova-Alum experimental model." (PMID 33649900, 2021). "The repeated IL-13 treatment leads to a typical mucus hypersecretion phenotype akin of the phenotype observed in inflammatory lung diseases such as asthma and COPD." (PMID 33731770, 2021). "In allergic rhinitis, a close entity in asthma, DNA hypomethylation of the IL-13 gene was observed after HDM sensitization." (PMID 34566492, 2021). "T2-high (IL-4–, IL-5–, IL-13–driven) asthma is typified by eosinophilic inflammation, while T2-low disease has been linked to neutrophilia and molecular signals such as type 1 IFN and IFN-γ." (PMID 34591794, 2021). "SOCS1 is a negative regulator of IL-4-dependent pathway, resulting in the regulation of IgE, IL-4 and IL-13 levels, as well as the eosinophilic mucosal inflammation in asthma." (PMID 34629023, 2021). "Novel biologics such as IL5 and IL-4/IL-13 pathway-targeting therapies have made essential the phenotyping of severe asthma, according to GINA guidelines." (PMID 33815653, 2021). "In asthma, Th2 cytokines IL-4, IL-13, and IL-5 play a major role in stimulating airway inflammation, whereas Th1 cells suppress airway hyperreactivity by producing IFN-γ." (PMID 33781317, 2021). "Due to its ability to relay signals for both IL-4 and IL-13, the blockade of IL-4Rα signalling has been of interest for alleviating asthma symptoms and severity." (PMID 33653328, 2021). "One recent study even revealed that IL-13 in children with wheezing can be considered as a possible predictor of asthma development." (PMID 34930201, 2021). "This confirms the low levels of Th2 cytokines previously observed in BAL from children with severe therapy-resistant asthma, although higher concentrations of IL-13 were found in BAL from children with moderate-to-SA vs healthy adults." (PMID 34349761, 2021). "This review aims to discuss the role of dupilumab, a human anti-interleukin-4 receptor α subunit monoclonal antibody that blocks both IL-4 and IL-13 signaling in severe asthma." (PMID 34572281, 2021). "As a proof of concept, these treatments have illustrated that the inhibition of the IL-4 and IL-13 pathways can effectively treat thunderstorm asthma, although costs and administration must improve before they can be considered as treatments." (PMID 34948449, 2021). "An increase in the levels of Th2 cytokines (IL-4, IL-5, and IL-13, among others) and Th17 cytokines (IL-17 and IL-6, among others) was observed in both patients with asthma and animal models of asthma." (PMID 34526979, 2021). "IL-4 and IL-13 are principal regulatory cytokines mainly secreted by activated Th2 cells, crucially important during the immune response in allergy and asthma." (PMID 33968984, 2021). "Another automated assay, the ARCHITECT Periostin Immunoassay, based on the principle of chemiluminescent immunoassay (CLIA) method, was developed to measure the concentration of periostin in serum and has been used in asthma patients as an anti-IL-13 therapy." (PMID 34439751, 2021). "In our previous study, we developed a four‐way gene model including IL13 rs20541, IL4 rs2243250, ADRB2 rs1042713, and FCER1B rs569108 for determining asthma susceptibility in Chinese Han children." (PMID 33277970, 2021). "Our findings demonstrate a steroid unresponsive source of IL‐13 that is associated with BAL neutrophilia and bacterial dysbiosis in severe asthma." (PMID 33411348, 2021). "Another attractive target for asthma therapy was IL-13, which has an important role in goblet cells hyperplasia and airway remodeling." (PMID 34680614, 2021). "Based on our results, we summarize that TGF-β signaling, cell cycle related, and IL-4 and IL-13 signaling pathways are important in determining responses to ICSs in patients with asthma." (PMID 33816533, 2021).
asthma (continued). "IL-17 and IL-13, two types of interleukin family, are common research subjects in the pathogenesis of asthma and are often studied as therapeutic targets for asthma." (PMID 34970542, 2021). "Overexpression of IL-13 in the lung in transgenic mice resulted in features typical of asthma, such as eosinophilic airway inflammation, increased mucus production, subepithelial fibrosis, and airway hyperresponsiveness." (PMID 34439751, 2021). "Increased IL-13 results in increased mucus secretion in the airway; in asthma attacks, this results in bronchial obstruction." (PMID 33743807, 2021). "The extent to which the protective effects of anti-IL-4 and IL-13 therapy in asthma reflects local blockade of the cytokines in the lung vs. systemic effects is still not fully understood." (PMID 33976140, 2021). "While aimed at atopic dermatitis, this is also relevant to allergen-induced asthma due to the integral role that IL-13 plays." (PMID 34948449, 2021). "Produced by type‐2 helper T‐cells (Th2), mast cells, basophils and ILC2 cells, IL‐13 is considered an archetypal T2 cytokine central to asthma pathophysiology." (PMID 33411348, 2021). "The binding of IL-13 to its receptor causes activation of the signal transducer and activator of transcription (STAT6), which facilitates mucus metaplasia in asthma." (PMID 34822557, 2021). "Specifically, IL-13 was used to stimulate fully differentiated mucociliary airway epithelial cells to induce the Th2 asthma phenotype and infection with rhinovirus 16 (HRV16)." (PMID 34577749, 2021). "Rather, as the severe asthma patients were all treated with high dose inhaled steroid therapies, the origin of observed IL‐13 must be steroid unresponsive, making eosinophils and Th2 cells unlikely." (PMID 33411348, 2021). "Approved therapeutic monoclonal antibodies targeting IgE or IL-4/IL-13 reduce asthma symptoms but require costly lifelong administrations." (PMID 33976140, 2021). "IL-4, IL-5 and IL-13 are the central Th2 cytokines responsible for eosinophilic inflammation in asthma." (PMID 34084159, 2021). "Five key inflammatory genes affecting IgE levels, including IL13, IL4, IL4RA, FCER1B and ADRB2, have been demonstrated associated with asthma or atopy by more than ten different studies." (PMID 34243801, 2021). "Nevertheless, in a mouse model of B. tropicalis house-dust-mite asthma, a significant up-regulation of IL-4 and IL-13 production was noted among lung-infiltrating Vγ1 γδ T cells." (PMID 33661375, 2021). "For example, patients switched from anti-IL-5 to anti-IL-4/IL-13 had worsening in asthma control and showed increased use of OCS, with substantial increases in peripheral eosinophils." (PMID 35126131, 2021). "In mild COVID-19, the cytokines weakly elevated in patients with asthma were IL-1β, IL-13, CXCL5, and LF." (PMID 34238349, 2021). "It is known that enhanced secretion of exosomes by epithelial cells contributes to the pathogenesis of asthma in an IL-13-dependent manner." (PMID 34234781, 2021). "Pathophysiological and inflammatory processes in T2-high asthma are represented by a high level of type 2 cytokines: IL-5, IL-4, IL-13, IL-25, IL-33, and thymic stromal lymphopoietin (TSLP)." (PMID 34070316, 2021). "In patients with severe asthma, there is strong association, measured by Spearman rank correlation, between BAL IL‐13 and IL‐ 4 concentrations, r = 0.749, p < 0.001 but weaker association between BAL IL‐13 and IL‐5 concentrations, 0.410, p < 0001." (PMID 33411348, 2021). "The chronic airway inflammation of asthma is characterized by the release of type 2 T helper cell cytokines, such as IL-4 and IL-13." (PMID 33407872, 2021). "The STAT1 and STAT4 pathways are considered vital for Th1 differentiation, while the IL-4/IL-13/STAT-6 pathway has been confirmed to be the major modulator of Th2 differentiation in asthma pathophysiology." (PMID 34093516, 2021).
asthma (continued). "Asthma pathophysiology involves alternative activation of macrophages by Th2 cytokines, such as interleukin 4 (IL‐4) or IL‐13." (PMID 33945658, 2021). "In this study, we stratified biologic naïve severe asthma patients treated with high‐dose inhaled corticosteroid therapy by their bronchoalveolar lavage IL‐13." (PMID 33411348, 2021). "In an ovalbumin-sensitized murine model of asthma, let-7 miRNA downregulated IL-13 and relieved allergic airway inflammation." (PMID 33996675, 2021). "Mild and moderate forms of asthma are associated with eosinophilic inflammatory cells in the BAL fluid or sputum and TH2 cytokines (IL-4, IL-5, and IL-13) with increased serum IgE." (PMID 35387053, 2021). "A protective effect of Nlrp1 in the asthma model was also indicated by an increase in IL-13 in the BAL fluid of Nlrp1−/− mice." (PMID 33378691, 2021). "Tralokinumab, an anti-IL-13 monoclonal antibody, is being developed to treat severe uncontrolled asthma." (PMID 34439751, 2021). "In a murine asthma model, glycoproteins from Sphingomonas induced type 2 inflammation via natural killer T cells in an IL-4-, IL-13-, and IL-33-dependent manner." (PMID 33831071, 2021). "The pleiotropic cytokine interleukin‐13 (IL‐13) is increased in bronchoalveolar lavage fluid and overexpressed in sputum and bronchial biopsy specimens of severe asthma patients." (PMID 33411348, 2021). "The application of this system for chronic obstructive pulmonary disease (COPD) epithelial cells with IL-13-induced asthma, or PLA-induced respiratory infection models, was used to evaluate therapeutics." (PMID 34178414, 2021). "Whereas IL-13 has been a therapeutic target for asthma with ongoing clinical trials, dupilumab, anti-IL-4Rα which inhibits both IL-4 and IL-13 signalling, has been a front-runner treatment showing efficacy in severe asthma patients." (PMID 34127548, 2021). "For what concerns asthma therapy through the inhibition of IL-13, two humanized monoclonal antibodies are currently considered." (PMID 34572281, 2021). "T2 asthma is characterized by airway inflammation driven by T2 cytokines including interleukins IL-4, IL-5, and IL-13." (PMID 33513844, 2021). "In a murine asthma model, IL-13 seems to induce TFF1 expression in Clara cells (Clara cell metaplasia), which are able to trans-differentiate into goblet cells." (PMID 34066339, 2021). "Th2-dominant responses, with increased Th2 (IL-4, IL-5, and IL-13) cytokines and IgE production, are characteristic immune responses in patients with allergic diseases such as food allergy, asthma, and AD." (PMID 34356353, 2021). "Treatments with kaempferol attenuated the Th2-driven allergic airway disease in an experimental model of asthma by decreasing production of IL-5 and IL-13 and amelioration of airway hyperresponsiveness (AHR) induced by OVA challenge." (PMID 34552650, 2021). "The effects of nicotine-containing e-cigarettes on murine model asthma increased Th2 cytokines (IL-4, IL-5, and IL-13), responsible for allergic inflammation." (PMID 33924379, 2021). "About half of all asthma patients have such an eosinophilic airway inflammation and corticosteroids, anti-IgE, anti-IL-5/IL-5R, and anti-IL-4/IL-13 treatment are effective at alleviating the symptoms." (PMID 34061861, 2021). "Hypermethylation in GATA3 CpG loci was associated with a decreased risk of asthma at birth, and hypomethylation of IL-13 and interleukin 5 receptor subunit alpha (IL5RA) was associated with an increased risk of asthma in teenagers." (PMID 33732246, 2021). "The approved humanized monoclonal antibodies (mAbs) for the treatment of asthma are targeted against IgE (omalizumab), IL-5 (mepolizumab and reslizumab), IL-5 receptor α (IL-5Rα; benralizumab), and IL-4/IL-13 (dupilumab)." (PMID 34572466, 2021). "IL-13–induced goblet cell metaplasia contributes to airway remodeling and pathological mucus hypersecretion in asthma." (PMID 33682796, 2021).